RGS4 (regulator of G protein signaling 4)
Diseases named in the same sentence as RGS4 in open-access papers (continued):
Sharing a sentence is not in itself a finding about the gene and the disease.
asthma (3 papers, 2012 to 2022). "Using immunocytochemical staining, ASM expression of RGS4 was determined in endobronchial biopsies from healthy subjects and those from subjects with mild, moderate and severe asthma." (PMID 22253691, 2012). "RGS4 expression was markedly increased in bronchial smooth muscle of patients with severe asthma, and expression correlated significantly with reduced pulmonary function." (PMID 22253691, 2012). "We have identified growth factor-mediated upregulation of RGS4 in ASM as a deleterious event in severe asthma." (PMID 22253691, 2012). "Smooth muscle bundles in bronchi from those with asthma had markedly increased numbers of RGS4+ ASM cells compared to those with mild-moderate asthma or healthy subjects." (PMID 22253691, 2012). "Increases in RGS4 expression by growth factors, which enhance ASM mitogenesis, may impart a susceptibility to ASM hyperplasia in asthma." (PMID 22253691, 2012). "Since RGS4 expression increased in proportion to ASM mass in asthma and correlated with the severity of disease, we next addressed whether ASM proliferation requires RGS4 expression." (PMID 22253691, 2012). "To characterize RGS4 expression in bronchial ASM bundles, we evaluated endobronchial biopsies from patients with asthma and age-matched healthy controls by immunohistochemistry." (PMID 22253691, 2012). "We explored the role of a Regulator of G-protein Signaling protein (RGS4) in the ASM hyperplasia and reduced contractile capacity characteristic of advanced asthma." (PMID 22253691, 2012). "RGS4 expression was restricted to a subpopulation of ASM and was specifically upregulated by mitogens, which induced a hyperproliferative and hypocontractile ASM phenotype similar to that observed in recalcitrant asthma." (PMID 22253691, 2012). "However, based on our data, we can speculate that it is repetitive exposure, rather than enhanced responsiveness, to S1P that determines increased expression of pro-remodelling factors observed in asthma, that is HBEGF, RGS4 and PLAUR." (PMID 25041788, 2014).
breast tumor (3 papers, 2016 to 2020). "In humans, RGS4 is involved in the suppression of breast tumor initiation and progression, overall indicating a role in the suppression of cell differentiation in sheep." (PMID 32928114, 2020).
lung cancer (3 papers, 2011 to 2024). A malignant neoplasm involving the lung. "Therefore, it is biologically plausible that RGS4, RGS5, and RGS12 are associated with lung cancer survival." (PMID 21698121, 2011). "As a GTPase-activating protein of the heterotrimeric Gq and Gi proteins, RGS4 and RGS5 are all tumor-suppressor proteins and have been shown to be low expressed in non–small-cell lung cancer (NSCLC)." (PMID 34199813, 2021). "One possibility is that the UBA6–UBE2Z cascade also induced the turnover of tumor-suppressor proteins RGS4 and RGS5, which are both shown to be related in lung cancer." (PMID 34199813, 2021).
osteosarcoma (3 papers, 2023 to 2024). A usually aggressive malignant bone-forming mesenchymal neoplasm, predominantly affecting adolescents and young adults. "Hsa-miR-874-3p, targeting the RGS4 gene (+603–+631), was found to inhibit cell migration in osteosarcoma." (PMID 39202417, 2024). "For example, in osteosarcoma tumour tissues, RGS4 interacts with a noncoding RNA (miR-874-3p) and affects the value-added and migration of cancer cells, and RGS4 overexpression promotes the value-added and migration of human osteosarcoma cells." (PMID 37924113, 2023).
papillary thyroid cancer (3 papers, 2021 to 2022). "Recently, a study described that LncRNA RPL34-AS1 can competitively bind miR-3663-3p and inhibit cell proliferation and invasion to promote apoptosis by regulating miR-3663-3p/RGS4 in papillary thyroid cancer cells." (PMID 33995620, 2021). "Also, RPL34-AS1 acted a suppressor of thyroid papillary carcinoma via competitively binding miR-3663-3p/RGS4 axis." (PMID 36162992, 2022). "RGS4 overexpression inhibits microRNA-3663-3p expression in thyroid cancer and increases RPL34-AS1 expression, a long non-coding RNA, which induces apoptosis and inhibits proliferation and invasion in papillary thyroid cancer cells." (PMID 34748583, 2021).
type 2 diabetes (3 papers, 2020 to 2021). "RGS4 inhibits the release of insulin mediated through beta-cell M3 muscarinic receptors by binding to M3 receptor to form complex in type 2 diabetes." (PMID 33892733, 2021). "In the future, it will be interesting to learn whether SPARC can improve insulin secretion in patients with type 2 diabetes through RGS4 pathway." (PMID 33067534, 2020).
bipolar disorder (2 papers, 2015 to 2016). A disorder of the brain that causes unusual shifts in mood, energy, activity levels and the ability to carry out day-to-day tasks. "We genotyped SNP1 (rs10917670), rs2661347, SNP4 (rs951436), SNP7 (rs951439), SNP18 (rs2661319), and rs10799897 (SNP9897) and tested the methylation status of CpG islands of the RGS4 gene in the postmortem DLPFC samples obtained from subjects with SCZ and bipolar disorder as well as healthy controls." (PMID 26973546, 2016).
bladder cancer (2 papers, 2021). "Previous studies had explored the associations between RGS family members and bladder cancer risk, including RGS1, RGS2, RGS4, RGS5, RGS6, and RGS20." (PMID 34482807, 2021).
colon cancer (2 papers, 2016 to 2020). "Both RGS2 and RGS4 abolished PAR4-activated ERK phosphorylation, calcium mobilization and RhoA activity, as well as PAR4-mediated colon cancer cell proliferation and related gene expression." (PMID 32517689, 2020).
Huntington disease (2 papers, 2009 to 2021). Huntington disease (HD) is a rare neurodegenerative disorder of the central nervous system characterized by unwanted choreatic movements, behavioral and psychiatric disturbances and dementia. "We finally screened five genes, including Arpp21, Rgs4, Rasd2, Gabrd, and Tmod1, two (Arpp21 and Rasd2) of which have been reported to be related with Huntington’s disease." (PMID 34433483, 2021).
osteoporosis (2 papers, 2022). A condition of reduced bone mass, with decreased cortical thickness and a decrease in the number and size of the trabeculae of cancellous bone (but normal chemical composition), resulting in increased fracture incidence. "Then the RNA-seq verification by using total RNAs isolated from the femurs of normal and ovariectomized Wistar rats indicated that MFAP5, CAMK2A, and RGS4 in the ceRNA network were closely associated with osteoporosis." (PMID 35680981, 2022). "Besides, RNA-seq analysis verification of the target genes indicated that the expression of MFAP5, CAMK2A, and RGS4 was significantly changed in the OVX rats and is closely associated with osteoporosis." (PMID 35680981, 2022). "Different from RGS4, the deletion of RGS10 or RGS12 in osteoclasts causes osteopetrosis phenotype through controlling the calcium oscillations and oxidative stress mediated Nrf2/Keap1 signaling pathways in mice, indicating their positive regulation in aging mediated osteoporosis." (PMID 35573989, 2022). "LINC00370 acts as a sponge that can inhibit the expression of miR-222-3p, which further upregulates RGS4 expression, osteoblast differentiation, and prevents ovariectomized (OVX)-induced osteoporosis." (PMID 35573989, 2022).
prostate carcinoma (2 papers, 2008 to 2016). A carcinoma that arises from epithelial cells of the prostate gland. "In order to better understand the timing of CCG-1423-regulated gene expression, we studied the effect of CCG-1423 on RGS4, RGS7, CTGF, and SOX9 gene expression in PC-3 prostate cancer cells from 1 to 24 h." (PMID 27600078, 2016). "In order to confirm the microarray results, we tested by qRT-PCR the effect of CCG-1423 on levels of RGS4, RGS7, CTGF, and SOX9 mRNA in PC-3 prostate cancer cells." (PMID 27600078, 2016).
thyroid cancer (2 papers, 2010 to 2021). "Our results indicate that RGS4 partially suppresses the survival of dedifferentiated thyroid cancer cells." (PMID 34748583, 2021). "RGS4 expression suppression partially inhibited cell death, apoptosis, and necrosis after NKX2-1 re-expression in dedifferentiated thyroid carcinoma cells." (PMID 34748583, 2021).
airway hyperresponsiveness (1 paper, 2023). "However, previous studies have shown that RGS4 promotes allergen- and aspirin-induced airway hyperresponsiveness." (PMID 38093354, 2023).
arteriosclerosis (1 paper, 2014). A vascular disorder characterized by thickening and hardening of the walls of the arteries. "Consequently, pharmaceutical modulation of RGS5 activity by small molecule approaches, as has been shown for RGS4, may have great clinical relevance with respect to stimulating arteriogenesis or counteracting neointima formation during arteriosclerosis or in-stent restenosis." (PMID 24972930, 2014).
astrocytoma (1 paper, 2015). "In the case of RGS4 the concentration response curves in astrocytoma cells are much shallower and the difference in potency between the various agonists is less pronounced,except for CGS21680, which has no clear effect." (PMID 26263491, 2015). "RGS-4 expression was inhibited in astrocytoma cells but enhanced in astrocytes by adenosine agonists." (PMID 26263491, 2015). "Incubation with the non-selective adenosine receptor agonist NECA leads to up-regulation of expression of RGS2 mRNA and down-regulation of RGS3 and RGS4 in U373 astrocytoma cells." (PMID 26263491, 2015). "However, expression of RGS4 in astrocytes was much lower than in U373MG astrocytoma cells precluding a reliable further assessment of the receptor type involved." (PMID 26263491, 2015). "However, while RGS4 is down-regulated by NECA in astrocytoma cells it is up-regulated in astrocytes." (PMID 26263491, 2015). "The present work shows that in U373 astrocytoma cells adenosine agonists up-regulate RGS2 mRNA expression and down-regulate expression of RGS3 and RGS4." (PMID 26263491, 2015). "In astrocytes the expression of RGS4 is extremely low and at the border of sensitivity of the assay and is, in contrast to astrocytoma cells, not down-regulated but rather up-regulated by adenosine agonists." (PMID 26263491, 2015).
campomelic dysplasia (1 paper, 2016). "These included regulator of G-protein signaling 4 (RGS4) and 7 (RGS7), which were both upregulated by CCG-1423, and CTGF (connective tissue growth factor), and SOX9 (sex determining region Y-box 9, also referred to as campomelic dysplasia, autosomal sex reversal) which were down-regulated." (PMID 27600078, 2016).
chronic heart failure (1 paper, 2022). "RGS4 is also upregulated in rat hypertrophic hearts and, importantly, in human failing hearts from both acute and end-stage chronic heart failure patients." (PMID 35628613, 2022).
diabetes (1 paper, 2020). "Recent studies conducted on RGS4 have illustrated its role in tumor development and in diverse pathologies, including CNS diseases, cardiovascular disease and diabetes." (PMID 32392739, 2020).
Dyskinesia (1 paper, 2024). A movement disorder which consists of effects including diminished voluntary movements and the presence of involuntary movements. "While l-DOPA–treated control mice rapidly developed dyskinesia, with a total dyskinetic event duration of 120 min, RGS4-lacking mice progressed to dyskinesia at slower rate, terminating the dyskinetic period faster, and with an attenuation of the AIMs peak." (PMID 39565858, 2024).
fibromyalgia (1 paper, 2024). A chronic disorder of unknown etiology characterized by pain, stiffness, and tenderness in the muscles of neck, shoulders, back, hips, arms, and legs. "Other genes associated with fibromyalgia that regulate nociceptive and analgesic neuronal pathways are the TAAR1 receptor gene, the regulator of G protein signaling 4 gene (RGS4), the cannabinoid receptor 1 gene (CNR1), and the ionotropic glutamate receptor AMPA 4 gene (GRIA4)." (PMID 39062116, 2024).
fibrosis (1 paper, 2021). the formation of excess fibrous connective tissue in an organ or tissue in a reparative or reactive process. "In addition, RGS4 overexpression diminished the anti-cardiac fibrosis effect of choline." (PMID 33892733, 2021).
insulinoma (1 paper, 2022). "Among these, RGS4 has been shown to be a potent negative regulator of muscarinic receptor signaling in insulinoma cells." (PMID 35418597, 2022).
ischemia (1 paper, 2015). A hypoperfusion of the BLOOD through an organ or tissue caused by a PATHOLOGIC CONSTRICTION or obstruction of its BLOOD VESSELS, or an absence of BLOOD CIRCULATION. "The loss of RGS4 following ischemia was associated with a marked reduction in total renal blood flow, and reduced inflammatory cytokine production from macrophages." (PMID 26300785, 2015).
Kaposi's sarcoma (1 paper, 2022). A malignant neoplasm characterized by a vascular proliferation which usually contains blunt endothelial cells. "However, G-protein signaling (RGS) 4 is not expressed in LECs, as Kaposi sarcoma-associated herpes virus upregulates PROX1, which is involved in LEC differentiation, leading to the downregulation of RGS4." (PMID 36067135, 2022).
left ventricular hypertrophy (1 paper, 2014). Enlargement of the LEFT VENTRICLE of the heart. "RGS4 has been implicated in left ventricular hypertrophy in mice as well as in inhibiting Gαq/11 signalling in cardiac myocytes." (PMID 24972930, 2014).
lentivirus infection (1 paper, 2024). Virus diseases caused by the Lentivirus genus. "Conversely, RGS4-lentivirus infection increased the percentage of cells showing calcium oscillations." (PMID 38391904, 2024).
lymph node metastasis (1 paper, 2017). "RGS4 expression reduction is significantly correlated with positive lymph node metastasis and advanced TNM stage." (PMID 29108247, 2017).
Obesity (1 paper, 2024). Accumulation of substantial excess body fat. "Here, we show in colonic EECs, obesity was associated with an altered RGS profile, with differential expression patterns in colonic RGS2 (underexpression), RGS4 (underexpression), RGS9 (overexpression), and RGS12 (overexpression)." (PMID 39142076, 2024). "While the single-cell data set identified RGS2, RGS4, RGS9, and RGS12 as having physiologically relevant transcriptional alterations within EECs in obesity, this finding was only validated for RGS9 in the colon." (PMID 39142076, 2024). "Using this criteria RGS2, RGS4, RGS9, and RGS12 were identified as having physiologically relevant transcriptional alterations in obesity compared to lean." (PMID 39142076, 2024). "Colonic expression of RGS2, RGS4, and RGS12 in obesity was not significantly different compared to lean." (PMID 39142076, 2024).
opioid dependence (1 paper, 2013). "Studies have shown that the expression of RGS4 is regulated by psychostimulants and opioids in the LC, a well-characterized brain region associated with opioid dependence and withdrawal." (PMID 23977258, 2013).
periodontitis (1 paper, 2024). An acute or chronic inflammatory process that affects the tissues that surround and support the teeth. "Secondly, our study identified six transcripts that are tissue biomarkers for periodontitis (ALOX12B, BNIP3, CEBPG, LURAP1L, RGS4, and TFAP2C) potentially significant for periodontitis using three machine learning methods: LASSO, SVM, and RF." (PMID 39045324, 2024). "LURAP1L and RGS4 showed significant overexpression, whereas ALOX12B, BNIP3, CEBPG, and TFAP2C were notably underexpressed in periodontitis." (PMID 39045324, 2024). "The results derived from the three machine learning methods were intersected and illustrated in a Venn diagram, revealing six transcriptional biomarkers critical for differentiating periodontitis tissues from healthy tissues: ALOX12B, BNIP3, CEBPG, LURAP1L, RGS4, and TFAP2C." (PMID 39045324, 2024).
pituitary adenoma (1 paper, 2026). "The functional significance of the top candidate gene, Regulator of G-protein Signaling 4 (RGS4), was examined using gain- and loss-of-function approaches and pharmacological inhibition in pituitary adenoma cell lines." (PMID 42099385, 2026).
prostate tumor (1 paper, 2022). "Presumably, prostate tumor cells that have lost the ability to express functional MXD1 or RGS4 would lose the capacity to enforce these observed Poly E-mediated antiproliferative effects on PC-3 cells, and perhaps other PCa cells as well." (PMID 36430806, 2022).
respiratory depression (1 paper, 2023). A decrease in ventilation secondary to impaired signals from the central nervous system. "To demonstrate the potential role of RGS4 in respiratory depression by MOR activation, we performed unilateral inhibition of RGS4 in the area of the preBötC in vivo." (PMID 37089428, 2023). "While RGS proteins, including RGS4, have been shown to modulate opioid analgesia, reward, and tolerance pathways, RGS role in respiratory depression was yet to be characterized." (PMID 37089428, 2023). "Overall, RGS4 does not mediate respiratory depression by MOR, but may be involved in MOR inhibition of other circuits such as neural circuits of nociception." (PMID 37089428, 2023). "On the other hand, RGS4 mediates opioid analgesia, but not respiratory depression, and RGS4 may be molecular targets to develop pain therapies without respiratory liability." (PMID 37089428, 2023).
sarcoma (1 paper, 2017). A usually aggressive malignant neoplasm of the soft tissue or bone. "RGS4 and SLC7A10 are two important genes directly associated with sarcoma in previous reports." (PMID 28404969, 2017).
uveitis (1 paper, 2022). An inflammatory process affecting a part of or the entire uvea. "Although the details of the mechanism by which RGS4 contributes to uveitis await further study in the future, the findings in our study and previous reports support the notion that RGS4 may be a potential therapeutic target in uveitis and other diseases." (PMID 35711454, 2022).
viral infection (1 paper, 2024). "As for the experiments aiming at overexpressing RGS4, the efficiency of the viral infection was confirmed by examining the fluorescence signal associated with the expression of the E2-Crimson protein driven by the lentivirus constructs." (PMID 38391904, 2024).